KRAS (KRas proto-oncogene, GTPase)
Diseases named in the same sentence as KRAS in open-access papers (continued):
Sharing a sentence is not in itself a finding about the gene and the disease.
pancreatic cancer (continued). "The gain-of-function KRAS mutation is the primary driver of pancreatic cancer development." (PMID 41391757, 2025). "KRAS mutations act as the initial trigger of pancreatic cancer." (PMID 40227826, 2025). "For instance, silencing KRAS mutations using siRNA has been shown to enhance tumour cell sensitivity to chemotherapeutic agents such as gemcitabine, leading to reduced tumour progression in pancreatic cancer models." (PMID 39820726, 2025). "Moreover, KRAS mutations have been shown to promote immune escape in pancreatic cancer cells by suppressing both the number and activity of T cells, through specific immune-evading mechanisms associated with individual KRAS variants." (PMID 40860798, 2025). "Additionally, recent findings have indicated that certain KRAS mutations are linked to chemoresistance in pancreatic cancer." (PMID 40664764, 2025). "One of the most mutated genes in pancreatic cancer is KRAS (involving the G12 codon)." (PMID 40004658, 2025). "In addition, a patient with metastatic pancreatic cancer received autologous T cells genetically engineered to express TCRs targeting the KRAS G12D mutation." (PMID 39744228, 2025). "Approximately 90% of pancreatic cancers harbor KRAS mutations." (PMID 39883522, 2025). "In addition, the mutated KRAS gene, which is strongly overexpressed in pancreatic cancer cells, has been reported to induce ROS production." (PMID 40647510, 2025). "Notably, REDD1 loss drives KRAS-driven progression in pancreatic cancer and lung adenocarcinomas, indicating a role as tumor suppressor." (PMID 40918647, 2025). "An early oncogenic event in pancreatic cancer is KRAS mutation." (PMID 39434498, 2025). "Similarly, in pancreatic cancer, radiomic features have demonstrated potential in predicting KRAS and SMAD4 mutations." (PMID 40192792, 2025). "Being the most frequently mutated gene in pancreatic cancers, KRAS is an attractive target." (PMID 39400496, 2025). "G12D is the most frequently mutated subtype allele involving the KRAS pathway in pancreatic cancer." (PMID 40004658, 2025). "The ongoing phase I/II CodeBreaK 100 clinical trial (ClinicalTrials.gov ID NCT03600883) is designed to investigate the safety, tolerability, and efficacy of sotorasib in patients with various solid tumors, including pancreatic cancer, harboring KRAS G12C mutations." (PMID 40806294, 2025). "However, KRAS gene mutations are common in pancreatic cancer; therefore, pancreatic cancer is likely to be potentially sensitive to ferroptosis." (PMID 40065720, 2025). "In pancreatic cancer, the most common KRAS mutation is G12D (referred to as KRAS G12D)." (PMID 40612677, 2025). "Common KRAS mutations detected in pancreatic cancer included G12D, G12V, G12R, and Q61H." (PMID 39699266, 2025). "Also, the group with the highest tumor purity also exhibited a higher frequency of KRAS pathogenic variants, which are driver mutations commonly associated with pancreatic cancer." (PMID 40981070, 2025). "However, at present, most reports on MRD testing for pancreatic cancer use ctDNA analysis for KRAS mutations, raising the issue of low sensitivity." (PMID 39920551, 2025). "Indeed, our analysis of the pancreatic cancer database in TCGA-PAAD revealed that tumors with KRAS G12 mutations had significantly higher glycolysis scores than other tumors." (PMID 39883522, 2025).
pancreatic cancer (continued). "However, among these 4 human pancreatic cancer organoids with natural KRAS G12V mutation and HLA-A*11:01 expression, PDAC-59 activated TCR-001–transduced allogeneic T cells to the highest level." (PMID 39846249, 2025). "More specifically, activating mutations in KRAS are detected in 95% of all pancreatic tumors." (PMID 40227826, 2025). "In addition, IL‐33, derived from the microenvironment, collaborates with KRAS mutations to activate epigenetic remodeling programs involved in early neoplasia and neoplastic transformation in pancreatic cancer." (PMID 41415713, 2025). "However, the relatively low mutation rate of KRAS G12C in pancreatic cancer (2.7%) limits its broad applicability in PDAC." (PMID 41463025, 2025). "Approximately 90% of pancreatic cancer patients harbor KRAS mutations." (PMID 40264765, 2025). "A high KRAS mutation frequency is one of the most prominent characteristics of pancreatic cancer." (PMID 41008826, 2025). "Pancreatic cancer is characterized by the prevalence of oncogenic mutations in KRAS." (PMID 39412982, 2025). "Mutations in the KRAS oncogene are present in over 90% of pancreas cancer cases." (PMID 40829173, 2025). "For example, during the development of pancreatic cancer, transient precursor cells of pancreatic cancer will appear in pancreatitis, characterized by the formation of transient enhancer networks mediated by KRAS mutation." (PMID 40032852, 2025). "While these observations require prospective validation, KRAS G12V mutation status may serve as a predictive biomarker for fluorouracil-based first-line chemotherapy in pancreatic cancer." (PMID 41303394, 2025). "Our findings align with those of previous studies, which demonstrated that impaired BCAA metabolism could support the oncogenic potential of KRAS mutations in pancreatic cancer." (PMID 40437561, 2025). "This study evaluated the combined effects of photodynamic therapy (PDT) using 5-aminolevulinic acid (5-ALA), a precursor to the natural photosensitizer protoporphyrin IX (PpIX), and dichloroacetic acid (DCA), a mitochondrial function modulator, in the KRAS-mutated PANC-1 pancreatic cancer cell line." (PMID 41303512, 2025). "Moreover, it has been identified as an autocrine stimulator of mutated KRAS signaling, reinforcing its potential as a target for chemoprevention in pancreatic cancer." (PMID 40719618, 2025). "KRAS is the most commonly mutated oncogene in pancreatic cancer and represents one of the earliest alterations observed in pancreatic intraepithelial neoplasia (Pan IN), where KRAS mutations lead to the activation of downstream effectors, driving various pro-tumorigenic processes." (PMID 40264765, 2025). "In the case of pancreatic cancer, 90% harbor mutations in the oncogene KRAS." (PMID 41472736, 2025). "The KRAS G12C mutation is detected in around 1–2 % of pancreatic cancer patients." (PMID 41080752, 2025). "A deeper understanding of DNA methylation events linked to oncogenic KRAS expression is provided by a study examining baseline DNA methylation at CpG islands in 11 KRAS-dependent pancreatic cancer cell lines with KRAS mutations, which revealed strikingly similar methylation patterns." (PMID 39858030, 2025). "KRAS mutations, present in over 90% of pancreatic cancers, remain a critical focus." (PMID 41584587, 2025).
pancreatic cancer (continued). "Therefore, the present study was conducted as a proof-of-principle in vitro investigation to assess the potential of combining ECT with sotorasib in the treatment of pancreatic carcinoma with different KRAS mutation statuses." (PMID 40806294, 2025). "Notably, we found variations in ferritin subunit expression among the pancreatic cancer cell lines with respect to the KRAS mutation status." (PMID 39294443, 2024). "Among the most common mutant genes in pancreatic cancer, KRAS mutations are frequently observed." (PMID 39113699, 2024). "KRAS mutations reduce the clinical efficacy of erlotinib in pancreatic cancer treatment." (PMID 39770538, 2024). "Additionally, KRAS mutations in pancreatic cancer induce fibroblast autocrine signaling, elevating cytokine interleukin-33 (IL-33) secretion within the stroma." (PMID 39770538, 2024). "Given the prevalence of KRAS mutation in pancreatic cancer, it is imperative to explore alternative therapeutic approaches that may yield better responses." (PMID 38672219, 2024). "Oncogenic KRAS mediated KRAS signaling pathway is crucial for cell growth, differentiation and survival, its continuous activation is closely associated with the development of breast cancer, colon cancer and pancreatic cancer." (PMID 38329437, 2024). "Furthermore, developing targeted therapies such as the TG01 vaccine, specifically addressing KRAS mutations common in pancreatic cancer, indicates a shift towards genetic precision in immunotherapy." (PMID 39335494, 2024). "In the case of MiaPaCa-2 cells (human pancreatic tumor cells with an activating mutation in the KRAS gene), the two most effective statins, pitavastatin and cerivastatin, had the most significant effect on the cell cycle; an increase in the number of cells was evident in the G0/G1 phase." (PMID 38782983, 2024). "The KRAS gene mutation has been found in 90% of pancreatic cancer patients." (PMID 39001498, 2024). "Our findings of different clinical outcomes by KRAS mutation subtypes and co-mutation status suggest an allele- and co-mutation-specific impact of KRAS mutations on pancreatic cancer outcomes and provide guidance in improving approaches to target KRAS in pancreatic cancer." (PMID 38310130, 2024). "This is promising; however, the heterogeneity of KRAS-mutated pancreatic cancer may dampen the dramatic responses seen in other malignancies." (PMID 38576709, 2024). "About 90% of PDAC tumors bear a KRAS mutation, which might encourage precancerous lesions associated with pancreatic cancer to progressively progress into invasive malignancy." (PMID 38504984, 2024). "However, most of these observations regarding NRF2 hyperactivation were made in acinar or epithelial cells that also carry an activating KRAS mutation, present in up to 95% of pancreatic cancers." (PMID 39337472, 2024). "Activating KRAS mutations are among the earliest oncogenic genomic alterations found in pancreatic intraepithelial neoplasia (PanIN) precursor lesions and seem to be a prerequisite for the development of a fully invasive metastatic pancreatic cancer phenotype." (PMID 38892436, 2024). "Furthermore, the high frequency of KRAS point mutations in pancreatic cancer suggests it to be a potential target for therapeutic strategy against pancreatic cancer." (PMID 39654897, 2024).
pancreatic cancer (continued). "Thus, we introduced a conditional knock-in for KRAS-K128R mutation in the pancreatic cancer cell line SW1990 harboring a homozygous KRAS-G12D mutation." (PMID 38858602, 2024). "Functional studies conducted in GP2-expressing pancreatic cancer cell lines demonstrated that rs78193826 may impact the activity of KRAS, a key driver of pancreatic cancer (with mutation frequencies >93%)." (PMID 38170255, 2024). "Additionally, the coexistence of KRAS gene mutation and pancreatitis, as well as KRAS gene mutation and pancreatic cysts, is associated with an increased risk of pancreatic cancer." (PMID 39640479, 2024). "In particular, approximately 90% of pancreatic cancer patients harbor KRAS mutations." (PMID 39409930, 2024). "As supported by substantial evidence in many experimental models, when it manifests in the context of pancreatitis, Mutations in KRAS, a common oncogenic driver of pancreatic cancer, lead to accelerated tumor development, and induce the appearance of neoplastic precursor lesions." (PMID 39107271, 2024). "Importantly, inhibition of GOT1 can promote pancreatic cancer cell ferroptosis; it was found that KRAS-mutated cancer cells rely heavily on GOT1 for long-term proliferation, and GOT1 inhibition sensitizes the malignant cells to glucose deprivation." (PMID 38607041, 2024). "Pancreatic cancer (PC) is highly lethal, with KRAS mutations in up to 95% of cases." (PMID 39057123, 2024). "To further investigate whether KRAS mutations result in high expression of ZDHHC20 in pancreatic cancer tissues, we treated pancreatic cancer cells with a KRAS G12D inhibitor." (PMID 38821916, 2024). "Similarly, it has been observed that KRAS mutation induces activation of the glutamine metabolism pathway in pancreatic cancer by enhancing the expression of pivotal enzymes responsible for glutamine degradation." (PMID 38459595, 2024). "Accumulating recent evidence suggests that specific oncogenic KRAS variants show distinct biological relevance and may predict outcome and response to therapy in pancreatic cancer." (PMID 38892436, 2024). "Similarly, a different set of exosomes was engineered to carry siRNA or shRNA molecules to specifically target KRAS mutation in pancreatic cancer." (PMID 38927885, 2024). "Indeed, KRAS mutation occurs frequently in pancreatic cancer and accounts for over 90% of cases of pancreatic cancer." (PMID 39730634, 2024). "Another study showed that higher levels of Pb may be a risk factor for both KRAS-mutated and wild-type cases of pancreatic cancer." (PMID 38250988, 2024). "This may suggest that HRR mutations could be one of the major oncogenic driver mutations in wild-type KRAS pancreatic cancer." (PMID 39456541, 2024). "Pancreatic cancer has a high KRAS mutation rate, with nearly 90% of cases being RAS-dependent." (PMID 39070787, 2024). "However, in pancreatic cancer these genes were found to be consistently upregulated when compared to normal tissue, an effect that was stronger in samples with KRAS mutations." (PMID 38384845, 2024). "KRAS is frequently mutated in a variety of cancers, especially pancreatic cancer and colon cancer." (PMID 38752985, 2024). "KRas, the most frequently mutated Ras gene, confers resistance to therapy in pancreatic cancer." (PMID 39632551, 2024). "Finally, T cell therapy with KRASG12D-targeting T cell receptors (TCRs) caused tumor regression in a patient with pancreatic cancer, and T cells with TCRs targeting other KRAS mutations, such KRASG12V, are under development." (PMID 38310130, 2024). "Pancreatic cancer cells bearing KRAS mutations exhibit high levels of ROS and NO, suggesting why biguanide AUTACs may be toxic to these cells, which likely have elevated levels of 8-nitro-cGMP." (PMID 39202851, 2024). "TEPs and their RNA profiles could differentiate between KRAS wildtype and KRAS-deficient pancreatic tumors." (PMID 38770216, 2024).
pancreatic cancer (continued). "However, in pancreatic cancer, the most common KRAS mutation is G12D, accounting for 45% of all KRAS mutations." (PMID 39594178, 2024). "Preclinical and clinical evidence suggests that pancreatic cancer KRAS G12D mutations may confer sensitivity to KRAS G12D-targeted, T-cell-receptor-based adoptive cell therapy, KRAS G12D small-molecule inhibitors, or SOS1 inhibitors." (PMID 38732320, 2024). "Furthermore, albumin and albumin-related drugs accumulate in KRAS-mutated pancreatic cancer cells and tissues." (PMID 39070787, 2024). "We investigated the potential clinical utility of short-term serial KRAS-mutated circulating cell-free tumor DNA (ctDNA) assessment for predicting therapeutic response in patients undergoing first-line chemotherapy for advanced pancreatic cancer." (PMID 38277079, 2024). "Besides chemotherapy and immunotherapy, targeted therapy against oncogenic KRAS, the most important driver mutation in pancreatic cancer, has attracting amounts attention from oncologists and pharmacologists for over three decades." (PMID 39054529, 2024). "The oncogenic KRAS mutation emerges as a primary event in pancreatic cancer pathogenesis." (PMID 38395786, 2024). "We found a significant association between the coexistence of KRAS gene mutation and pancreatitis (OR = 14.18, 95% CI: 2.78–105.26, P < 0.01), as well as between KRAS gene mutation and pancreatic cysts (OR = 20.62, 95% CI: 7.56–60.30, P = 0.0026), with an increased risk of pancreatic cancer." (PMID 39640479, 2024). "However, it’s noteworthy that in SMARCB1-deficient undifferentiated pancreatic carcinoma, KRAS is typically wild-type, as reported in a recent study." (PMID 39777351, 2024). "KRAS mutations occur in a variety of tumors, such as lung, colorectal, and pancreatic cancer." (PMID 36782249, 2023). "Preclinical data suggest pancreatic tumors with KRAS G12R mutations might be more sensitive to MEK inhibition as they fail to engage with a key KRAS effector—PI3K catalytic subunit p110α." (PMID 37894382, 2023). "In our study, we investigated the therapeutic effects of KV to inhibit the growth and proliferation of KRAS-mutated pancreatic cancer cell lines (AsPC-1, Panc-1, and MiaPaCa-2) and oxaliplatin-resistant pancreatic cancer cells (oxaliplatin-resistant AsPC-1 cells)." (PMID 37174108, 2023). "About 90% of human pancreatic cancer cells exhibit Kirsten rat sarcoma (KRAS) mutations." (PMID 37242560, 2023). "Almost ten years ago, aberrant activation of the KRAS pathway was shown to promote glucose avidity in pancreatic tumors, whereby KRAS mutations were associated with the upregulation of the glucose transporter GLUT1, and enzymes that execute aerobic glycolysis, such as LDHA." (PMID 37408249, 2023). "In addition, reduced immune cell infiltration in pancreatic cancer has been correlated with KRAS mutations." (PMID 37242560, 2023). "While our future studies will address this possibility experimentally, it is important to note that 90–95% of pancreatic cancers have a KRAS mutation, which makes them intrinsically more permissive to VSV and other OVs via KRASMUT-mediated inhibition of antiviral signaling." (PMID 37671865, 2023).